MFN2 (mitofusin 2)
Diseases named in the same sentence as MFN2 in open-access papers (continued):
Sharing a sentence is not in itself a finding about the gene and the disease.
liver fibrosis (11 papers, 2021 to 2025). "Upregulating Mfn2 expression at the early stage of fibrosis impeded the process, triggered the downregulation of type I collagen, and antagonized the formation of factors associated with liver fibrosis." (PMID 35083025, 2022). "During the process of hepatic fibrosis in vivo, extracellular collagen deposition and the expression of fibrosis-related proteins increased progressively, while Mfn2 expression decreased gradually." (PMID 35083025, 2022). "The histological sections revealed that transfection on day 1 of the establishment of the hepatic fibrosis model led to a much lower amount of collagen deposition in the Mfn2 group compared with the CCl4 and GFP groups by the end of the experiment (P < 0.001)." (PMID 35083025, 2022). "The expression of MFN2 was decreased in the S1–S4 group, and MFN2 expression level was gradually becoming lower in the development of liver fibrosis." (PMID 34676206, 2021). "And the MFN2 expression in liver tissues was gradually becoming lower and lower during the process of liver fibrosis." (PMID 34676206, 2021). "Taken together, exosomal miR-500 derived from LPS-activated macrophages promotes HSC proliferation and activation by targeting MFN2 in liver fibrosis." (PMID 34676206, 2021). "We also detected the interaction effects of exosomal miR-500 and MFN2 in liver fibrosis mouse model." (PMID 34676206, 2021). "In addition, Mfn2 can also restrain the proliferation of hepatic stellate cells, inhibit liver fibrosis, and play a protective role in the liver." (PMID 40362804, 2025). "For example, suppression of MFN2 has been shown to enhance neural differentiation of embryonic stem cells by activating the AKT signaling pathway, while MFN2 inhibits hepatic stellate cell proliferation and attenuates liver fibrosis in rat models through the PI3K/AKT signaling pathway." (PMID 39430741, 2024). "However, other authors demonstrate that overexpression of Mfn2 improves liver fibrosis in hepatic stellate cells of mice." (PMID 35215423, 2022). "However, this was only observed in the rats that received Mfn2 intervention in the early stage of liver fibrosis; as the actuation duration of CCl4 was prolonged, the effect of Mfn2 was gradually attenuated." (PMID 35083025, 2022). "It has been reported that the overexpression of Mfn2 in HSCs could ameliorate CCl4-induced liver fibrosis." (PMID 35933403, 2022). "We hypothesized that MFN2 plays a role in antiproliferation via the PI3K-AKT signaling pathway during the process of hepatic fibrosis." (PMID 35083025, 2022). "Mfn2 probably provides new therapeutic methods for hepatic fibrosis in the near future." (PMID 35083025, 2022). "In addition, we determined the levels of serum exosomal miR-500 and the expression of MFN2 in liver fibrosis tissues." (PMID 34676206, 2021). "Furthermore, MFN2 overexpression using AAV-MFN2 was found to improve carbon-tetrachloride-induced liver fibrosis in vivo." (PMID 34073868, 2021). "miR-500 promotes HSC activation and liver fibrosis via suppressing MFN2." (PMID 34676206, 2021). "Hence, Mfn2 probably provides new therapeutic methods for hepatic fibrosis in the near future." (PMID 35083025, 2022). "Moreover, Mfn2 exhibits antifibrotic potential in the early stage of hepatic fibrosis." (PMID 35083025, 2022). "Furthermore, Wistar rats were transfected to reveal the role of Mfn2 in hepatic fibrosis." (PMID 35083025, 2022). "Furthermore, the H&E and Sirius Red staining also showed that exosomes with miR-500 overexpression could accelerate liver fibrosis, while MFN2 could partially inhibit it." (PMID 34676206, 2021). "And miR-500 could accelerate liver fibrosis through MFN2 both in vitro and in vivo." (PMID 34676206, 2021). "Mfn2 suppresses HSC proliferation and activation and exhibits antifibrotic potential in early-stage hepatic fibrosis." (PMID 35083025, 2022).
liver fibrosis (continued). "This study was designed to increase our understanding of the function of Mfn2 in HSC proliferation and in CCl4-induced liver fibrosis." (PMID 35083025, 2022). "We attempted to understand the mechanism of MFN2 in hepatic stellate cell (HSC) proliferation and the development of hepatic fibrosis." (PMID 35083025, 2022). "However, the correlation between MFN2 and PI3K-AKT signaling in hepatic fibrosis remains largely unexplored." (PMID 35083025, 2022). "Based on the study, our hypothesis was provided that exosomes containing upregulated miR-500 was secreted from LPS-activated macrophages and then was uptaken by HSCs, subsequently suppressing MFN2 in HSCs and leading to HSC activation and the development of liver fibrosis." (PMID 34676206, 2021).
non-alcoholic fatty liver disease (11 papers, 2020 to 2025). "Deficiency and abnormalities in Mfn2 expression underlie the pathogenesis of non-alcoholic fatty liver disease (NAFLD), T2DM, diabetic nephropathy, and Charcot–Marie–Tooth disease type 2A (CMT2A) by loss of MAM integrity." (PMID 40148800, 2025). "Here, we discuss how the mitochondrial fusion factors, mitofusins, impact on mitophagy and apoptosis, present pro-survival and pro-apoptotic roles of mitophagy and detail the roles of mitophagy and mitofusin 2 in non-alcoholic fatty liver disease (NAFLD)." (PMID 33072754, 2020). "Furthermore, we highlight the impact of this interplay on disease, focusing on how mitofusin 2 and mitophagy affect non-alcoholic fatty liver disease." (PMID 33072754, 2020). "In addition, a protective role of MFN2 against non-alcoholic fatty liver disease (NAFLD) was recently described, involving both the MFN2 full length protein as well as shorter forms that result from alternative Mfn2 splice variants." (PMID 39929801, 2025).
ovarian carcinoma (11 papers, 2020 to 2024). A malignant neoplasm originating from the surface ovarian epithelium. "Activation of mitofusin 2 (Mfn2) by genetic or pharmacological tools restrained the mitochondrial fission and reduced ROS concentration, subsequently suppressing ovarian cancer progression." (PMID 37386404, 2023). "The mediating role of MFN2 in mitophagy reduces ROS levels and suppresses ovarian cancer progression through the AMPK/mTOR/ERK signaling pathway." (PMID 38038814, 2023). "In contrast, cordycepin have shown to inhibit mitochondrial function by reducing Mfn2 expression and inducing mitochondrial fragmentation to suppress metastasis and migration of ovarian carcinoma cells." (PMID 34744731, 2021). "The clinical relevance of CBS and MFN2 expression in ovarian cancer was examined in the clinically annotated mRNA data from The Cancer Genome Atlas (Gene Expression Omnibus) databases." (PMID 35366284, 2021). "Silencing MFN2 stimulates mitochondrial fission, and sensitizes the resistant ovarian cancer cells to DDP." (PMID 35003356, 2021). "Mitochondrial dynamics mediated by DRP1 and MFN2 influence the level of ATP and ROS in ovarian cancer cells." (PMID 35003356, 2021). "Leflunomide was also shown to restore MFN2 levels in human ovarian cancer cells." (PMID 38607070, 2024). "DRP1 and MFN2 deregulation is also involved in ovarian cancer cisplatin resistance." (PMID 36674740, 2023). "MFN2 (Mitofusin 2) gene was found to promote mitophagy in ovarian cancer by increasing mitochondrial fusion and autophagosomal engulfment, and further leading to the activation of key autophagy-related proteins such as LC3B and p62 and results in the degradation of damaged mitochondria." (PMID 38038814, 2023). "In accordance with the expression of DRP1 and MFN2, the average mitochondrial length was significantly increased in these cells, supporting again that mitochondrial dynamics contribute to the development of cisplatin resistance in ovarian cancer cells." (PMID 36674740, 2023). "Additionally, in ovarian cancer cell lines, CBS expression maintains mitofusin-2 expression, with CBS knockdown lowering mitofusin-2 expression, causing mitochondrial fragmentation with a fused spherical morphology and increased unbranched mitochondria." (PMID 34829691, 2021). "In addition, the expression of other ER–mitochondria tethering proteins such as VAPB-PTPIP51 and MFN2 increased in eupatilin-treated ovarian cancer cells." (PMID 32503295, 2020). "Thus, we examined whether mitochondrial dynamics mediated by DRP1 and MFN2 contributes to DDP chemoresistance through inhibiting the intrinsic apoptosis pathway in ovarian cancer cells." (PMID 35003356, 2021). "Therefore, our data indicate mitochondrial dynamics mediated by DRP1 and MFN2 may play a critical role in the development of DDP chemoresistance in ovarian cancer." (PMID 35003356, 2021). "Mitofusin 2 (MFN2) promotes mitochondrial fusion, decreases ROS production, and impedes cell proliferation in ovarian cancer cells." (PMID 38012141, 2023). "To examine the role of mitochondrial dynamics in DDP resistance in ovarian cancer cells, we first examined the expression of mitochondrial dynamics-related proteins including MFN1, MFN2, DRP1, and OPA1 in SKOV3 and SKOV3/DDP cells." (PMID 35003356, 2021). "Furthermore, in ovarian cancer cells the inhibition of CBS results in oxidative stress conditions, activating JNK that in turn phosphorylates MFN2 and results in its degradation." (PMID 36674740, 2023). "Therefore, the consistent alterations of DRP1 and MFN2 in both SKOV3/DDP and SKOV3 under DDP stress strongly suggest its crucial role in the development of DDP chemoresistance in ovarian cancer." (PMID 35003356, 2021).
Ataxia (10 papers, 2014 to 2025). Ataxia refers to impaired coordination of voluntary muscle movement. "We report here that early onset ataxia with intellectual disability can also be associated with MFN2-related Charcot–Marie–Tooth, Type 2A2A diagnosis, the most common type of autosomal dominant axonal neuropathy." (PMID 32532879, 2020). "This early-onset cerebellar ataxia represents an expanded phenotype of the MFN2 pathogenic T105M mutation." (PMID 32532879, 2020). "Mice with PN-specific Mfn2 knockout exhibited dysfunctional mitochondrial oxidative phosphorylation, progressive PN degeneration, and cerebellar ataxia." (PMID 39147737, 2024). "In particular, the frequency of the cerebellar ataxia was high in patients with NEFL mutations (72.7%), compared to GJB1 mutations (9.1%), PMP22 duplication (0%), and MFN2 mutations (0%)." (PMID 34768465, 2021). "While ataxia has not been associated previously with MFN2 specifically, it is common in mitochondrial disease." (PMID 38274408, 2021). "In addition, cerebellar ataxia, which is commonly manifested in patients with NEFL mutations, is not well observed in the other genetic mutations, such as PMP22 and MFN2, except in 1 out of 11 patients with GJB1 mutations." (PMID 34768465, 2021). "Abnormalities of the nervous system, including neurodevelopmental abnormality (HP:0012759), ataxia (HP:0001251), seizure (HP:0001250), peripheral neuropathy (HP:0009830) etc., were present in 44% of the families reported, and the top five contributing genes were POLG, SPG7, MFN2, FXN and C19ORF12." (PMID 39423307, 2025).
pancreatic cancer (10 papers, 2018 to 2025). "In this study, Mfn2 is associated with a good survival rate in pancreatic cancer." (PMID 30046371, 2018). "However, the role and underlying mechanisms of Mfn2 on autophagy of pancreatic cancer cells is still unclear." (PMID 30046371, 2018). "Meanwhile, Mfn2 is associated with a good survival rate in pancreatic cancer." (PMID 30046371, 2018). "However, the role and underlying mechanisms of Mfn2 on cell autophagy of pancreatic cancer is still unclear." (PMID 30046371, 2018). "In pancreatic cancer, MFN2 has been demonstrated to induce autophagy through inhibition of the PI3K/Akt/mTOR pathway." (PMID 34956177, 2021). "Mfn2− pancreatic cancer is an aggressive subtype, alongside Mfn2+ pancreatic cancer, a less aggressive subtype." (PMID 30046371, 2018). "Based on the data we observed above, the Mfn2 immunophenotype is closely relevant to the malignant behavior of pancreatic cancer." (PMID 30046371, 2018). "The effect of autophagy in pancreatic cancer is also the potential mechanism of proapoptotic and antiproliferative functions of Mfn2 in pancreatic cancer." (PMID 30046371, 2018). "Above all, it is indicated that Mfn2 can be a potential clinical therapeutic target in pancreatic cancer." (PMID 30046371, 2018). "In this research, we used adenovirus to deliver Mfn2 to pancreatic cancer cells, so that we can assess the effect of Mfn2 on autophagy." (PMID 30046371, 2018). "In this study, we first proposed that Mfn2 can increase cell autophagy by the PI3K/Akt/mTOR signaling pathway in pancreatic cancer." (PMID 30046371, 2018). "Western blotting, caspase-3 activity measurement, and CCK-8 and reactive oxygen species (ROS) assay were used to examine the effects of Mfn2 on pancreatic cancer autophagy, apoptosis, cell proliferation, oxidative stress, and PI3K/Akt/mTOR signaling." (PMID 30046371, 2018). "We consider that Mfn2 induces pancreatic cancer cell autophagy by inhibiting the PI3K/AKT/mTOR signaling pathway." (PMID 30046371, 2018). "The latest study showed that in pancreatic cancer, overexpressed Mfn2 makes cells under apoptotic stress with cleaved caspases." (PMID 30046371, 2018). "Our aim was to explore the effect of Mfn2 on multiple biological functions involving cell autophagy in pancreatic cancer." (PMID 30046371, 2018). "Our finding suggests that Mfn2 induces cell autophagy of pancreatic cancer through inhibiting the PI3K/Akt/mTOR signaling pathway." (PMID 30046371, 2018). "Assessment of Kaplan-Meier curves showed that Mfn2− pancreatic cancer has a worse prognosis than Mfn2+ pancreatic cancer has." (PMID 30046371, 2018). "For assessing cell apoptosis in pancreatic cancer cells with Mfn2 overexpression, the expression of Bcl-2 and Bax was measured using Western blotting analysis." (PMID 30046371, 2018). "In this study, Mfn2 was discovered increasing the cell autophagy by the PI3K/Akt/mTOR signaling pathway in pancreatic cancer." (PMID 30046371, 2018). "In PANC-1 pancreatic cancer cells, miR-125a activated mitochondrial fission by targeting mitofusin 2 (Mfn2)—a protein localized in the outer mitochondrial membrane required for mitochondrial fusion—thereby triggering mitochondria-mediated apoptosis and impairing cancer cell invasion." (PMID 34575852, 2021). "Pancreatic cancer seems to be one of the most affected by MFN2 activity." (PMID 33233365, 2020). "Indeed, pancreatic cancer cells expressing MFN2 showed decreased proliferation and ROS production, together with increased expression levels of the autophagy regulators LC3-II and Bax." (PMID 33233365, 2020). "Mfn2 is considered to perform antiproliferative and proapoptotic functions in pancreatic cancer." (PMID 30046371, 2018). "Meanwhile, Mfn2 also influences multiple biological functions of pancreatic cancer cells." (PMID 30046371, 2018). "Further studies concerning the in vivo effect of Mfn2 for the pancreatic cancer is still required." (PMID 30046371, 2018).
pancreatic cancer (continued). "Mfn2 is expressed both in normal pancreas and in pancreatic cancer tissues." (PMID 30046371, 2018). "Mfn2 can act as a therapeutic target in pancreatic cancer treatment." (PMID 30046371, 2018). "It is indicated that the overexpression of Mfn2 may become an effective treatment strategy in pancreatic cancer." (PMID 30046371, 2018). "Pancreatic cancer cell line, Aspc-1, was treated with Ad-Mfn2 overexpression." (PMID 30046371, 2018). "Mfn2 may act as a therapeutic target in pancreatic cancer treatment." (PMID 30046371, 2018). "Besides, we uncovered the mechanism of Mfn2-induced autophagy of pancreatic cancer cells." (PMID 30046371, 2018). "In addition, Mfn2 inhibited pancreatic cancer cell proliferation and ROS production." (PMID 30046371, 2018). "In this study, we also used bioinformatics methods to analyze potential regulatory genes of Mfn2, aiming to provide valuable information for further biological mechanism elucidation of Mfn2 and provide the groundwork for therapeutic target identification for pancreatic cancer." (PMID 30046371, 2018). "Therefore, overexpression of MFN2 may provide an effective treatment strategy in pancreatic cancer." (PMID 34956177, 2021). "Mfn2 improved the expression of LC3-II and Bax and downregulated the expression of P62 and Bcl-2 in pancreatic cancer cells." (PMID 30046371, 2018). "Meanwhile, Mfn2 also significantly inhibited the expression of p-PI3K, p-Akt, and p-mTOR proteins in pancreatic cancer cells." (PMID 30046371, 2018). "Interestingly it was demonstrated that miR-125a is decreased in pancreatic cancer cells (PANC-1), accompanied by an increase in the contents of mitofusin 2 (MFN2) an important regulator of mitochondrial fission." (PMID 31921637, 2019). "In addition, MFN2 decreased the levels of phospho-phosphoinositide 3-kinase (p-PI3K), phospho-protein kinase B (p-Akt), and phospho-mammalian target of rapamycin (p-mTOR) proteins, which promote pancreatic cancer cell growth, proliferation, and metastasis." (PMID 33233365, 2020).
pulmonary arterial hypertension (10 papers, 2016 to 2025). Pulmonary arterial hypertension (PAH) is a group of diseases characterized by mean pulmonary artery pressure >20 mmHg and elevated pulmonary arterial resistance leading to right heart failure. "Chronic hypoxia is known to be a common cause of pulmonary hypertension, and hypoxia-induced effects can be reversed by the overexpression of MFN2 in PASMCs." (PMID 35453623, 2022). "Pulmonary arterial hypertension is accompanied by reduced MFN2 and excessive DRP1 caused by increased hypoxia inducible factor 1 alpha (HIF-1α) activation and decreased PGC-1α activity." (PMID 34938787, 2021). "During hypoxia-induced pulmonary hypertension in rats, downregulation of Mfn2 activates the PI3K/Akt pathway, thereby causing more cells to enter the S + G2/M phase of the cell cycle and inhibiting the mitochondrial apoptosis pathway." (PMID 28190190, 2017). "There are several different possible mechanisms leading to decreased MFN2 expression in pulmonary hypertension." (PMID 35204311, 2022). "Nevertheless, bortezomib and marizomib decrease the viability of PASMCs by restoring the expression of MFN2 under hypoxic conditions; these findings provide novel therapeutic strategies for pulmonary hypertension." (PMID 35453623, 2022). "Downregulation of mitochondrial dynamics regulator MFN2 has been found resulting in mitochondrial fragmentation and contributing to the development of heart failure in rats and in patients with pulmonary arterial hypertension (PAH)." (PMID 36093152, 2022). "The decrease in MFN2 in pulmonary arterial hypertension leads to mitochondrial fragmentation and proliferation." (PMID 34938787, 2021). "Decreased expression of Mfn2 has also been found to contribute to mitochondrial fragmentation and a proliferation-cell death imbalance in human and experimental pulmonary arterial hypertension." (PMID 26942197, 2016). "The expression of MFN2 decreased and the phosphorylation of MFN2 increased in PASMCs from patients with pulmonary arterial hypertension (PAH)." (PMID 35453623, 2022). "In pulmonary arterial hypertension, increased HIF1A promotes DRP1-driven mitochondrial fission and fragmentation in human lung and pulmonary arterial smooth muscle cells, while decreasing MFN2 activity." (PMID 29463805, 2018).